INS (insulin)
Diseases named in the same sentence as INS in open-access papers (continued):
Sharing a sentence is not in itself a finding about the gene and the disease.
diabetes (continued). "Similar to humans, HNF1A-null mice exhibit abnormal glucose-stimulated insulin secretion and develop diabetes two weeks after birth, expressing low levels of insulin and insulin-like growth-factor-1 (Igf1)." (PMID 36361703, 2022). "In 2014, a study that investigated the availability of selected essential medicines for diabetes in LMICs revealed that the median number of essential diabetes medicines was 6, uniformly partitioned between insulin and oral medicines." (PMID 35317808, 2022). "Type 1 diabetes mellitus occurs because the beta cells of the pancreas are destroyed by the immune system and are unable to secrete insulin." (PMID 36246911, 2022). "After her parents were educated in insulin therapy and diabetes management, the patient was discharged home and referred to the rheumatologic follow-up." (PMID 34999914, 2022). "It has been shown that dysfunction of this enzyme in pancreatic β-cells leads to impaired insulin secretion and diabetes." (PMID 36672824, 2022). "Despite a history of diabetes, intensive insulin therapy to control the blood glucose of hyperglycemic patients in critically ill condition significantly attenuated the inflammation and infection, decreasing the morbidity and mortality." (PMID 35600601, 2022). "A longer study is warranted in the future to investigate the long-term effects of insulin on myocardial structure and function in diabetes." (PMID 35574440, 2022). "At present, there is still no cure for diabetes; subcutaneous injection of insulin remains the main method to control insulin-dependent diabetes in the clinic." (PMID 36012342, 2022). "The key to successful treatment of diabetes is to develop insulin substitutes and auxiliary plants for reducing adverse effects." (PMID 36678512, 2022). "Nevertheless, recent studies have shown that these genes also participate in fasting glucose control in diabetes via activating Akt signaling pathways and increasing insulin secretion." (PMID 35909518, 2022). "In the “GP only” profile, the proportion of participants with a duration of diabetes >10 years (37.0%) and using insulin or other injectable (22.6%) was lower than in other profiles (51.0% to 61.6%, and 63.5% to 75.0%, respectively)." (PMID 35498410, 2022). "Adults with insulin-treated type 2 diabetes mellitus experience a lower frequency of mild and severe hypoglycemia episodes than those with type 1 diabetes mellitus." (PMID 35571045, 2022). "According to the theory of bihormonal regulation, diabetes results from the abnormal secretion of both insulin and glucagon." (PMID 35784565, 2022). "Diabetes mellitus (DM) is a category of metabolic illnesses distinguished by persistent hyperglycemia that develops as a result of irregular insulin production and/or insulin resistance over an extended period of time." (PMID 36467726, 2022). "The inclusion of regular physical activity is critical for optimal insulin action and glycemic control in individuals with diabetes." (PMID 37092111, 2022). "Deletion of Prohibitin-2 in β cells has been shown to impair insulin secretion and mitochondrial function, resulting in a progressive worsening of glucose tolerance, and it promotes the development of diabetes." (PMID 35298439, 2022). "The clinical symptoms of type 1 diabetes mellitus are preceded by a long period of “prediabetes”, characterized by the presence of anti-islanding antibodies and impaired insulin and C-peptide secretion." (PMID 35453807, 2022). "Small molecule inhibitors to insulin-degrading enzyme (IDE) have been previously suggested as a potential treatment for diabetes through their ability to reduce insulin degradation and thus increase insulin activity." (PMID 35350789, 2022). "In particular, diabetes mellitus develops owing to reduced insulin sensitivity, and insufficient insulin production." (PMID 36232070, 2022). "Resveratrol (RES) has a potential therapeutic effect in obesity and diabetes by improving oxidative metabolism and insulin signaling." (PMID 36143977, 2022).
diabetes (continued). "Diabetes occurs when islet β-Cells cannot secrete insulin or the body cannot use insulin efficiently and its prevalence is increasing year by year, affecting approximately 8.3% of the global population." (PMID 36496564, 2022). "Journals and co-cited journals analysis showed that Diabetes published the most insulin-secreting cells studies, and received the largest number of co-citations." (PMID 36743933, 2022). "Overall, the resilience-based Islamic intervention exerted an impact on the levels of HbA1c, lipid profile, TAS, insulin, diabetes fatigue, and HRQoL among patients with T2DM." (PMID 36048792, 2022). "Stevia leaves possess antihyperglycemic, insulin‐mimetic, insulinotropic, and glucogonostatic properties, which play important role in the management of diabetes although there is limitation of proper randomized control trials." (PMID 36171777, 2022). "Policies aimed at universal access to low-cost insulin and oral antidiabetic medications, and to basic diabetes care are mandatory." (PMID 35850129, 2022). "Recently, the development of insulin-producing pancreatic β-cells from stem cells has become a potential approach to treat diabetes." (PMID 35395037, 2022). "Diabetes mellitus (DM), sometimes known as diabetes, is a chronic disease in which the body is unable to make or efficiently utilise the hormone insulin, resulting in elevated amounts of glucose in the blood." (PMID 36348847, 2022). "In this study, we defined the molecular mechanism by which inhibitor C646 directly activates insulin signaling in hepatocytes of obesity and diabetes." (PMID 35074429, 2022). "An impaired inhibitory effect of sympathetic nerves on insulin secretion was also found in patients with long‐term type 1 diabetes mellitus." (PMID 35758323, 2022). "The major abnormalities in all diabetes patients are hyperglycemia, systemic insulin resistance, and impaired cardiac insulin metabolic signaling." (PMID 36552599, 2022). "The drugs used by the participants for diabetes control were metformin, insulin, glibenclamide, acarbose, and sitagliptin." (PMID 35846887, 2022). "When the mucosal penetration of insulin/FITC-labeled TCTP-PTD 13 was visualized in mice with STZ-induced diabetes, TCTP-PTD 13 rapidly penetrated the nasal epithelium after nasal administration, and then was partially distributed in the submucosal layer." (PMID 36452220, 2022). "Type 2 diabetes mellitus (T2DM) is a progressive condition that is produced by relative insulin deficiencies caused by pancreatic β-cell (cells that synthesize and secrete insulin and amylin) dysfunction and insulin resistance." (PMID 36428864, 2022). "Type 1 Diabetes Mellitus (T1DM) is a chronic autoimmune disease characterized by immune-mediated destruction of insulin-producing beta cells of the pancreas; its main precipitating factors are genetic susceptibility and environmental insults." (PMID 35101023, 2022). "For the studied diabetes factors, a significantly higher rate of insulin pump usage was found among patients with type 1 diabetes (10.2%), duration of diabetes of more than 10 years (8.1%), and among those patients with HbA1c levels between 6.5 and 7.5 (9.5%)." (PMID 35719798, 2022). "Despite increased overall interest and research on the effects of obesity and diabetes in pregnancy, knowledge regarding the effects of insulin on the placenta remains limited." (PMID 35258482, 2022). "On the seventh day after STZ injection, the rats in the three T2DM groups lost weight, fasting blood glucose exceeded 11.1 mmol/L, and insulin sensitivity decreased, demonstrating the success of the diabetes model establishment." (PMID 36010637, 2022). "Diabetes is a medical condition due to the inability of the pancreas to produce sufficient insulin or the inability of the body to effectively use the insulin produced." (PMID 35215637, 2022). "Metformin is an orally effective insulin-sensitizing drug widely prescribed for treating type 2 diabetes mellitus (T2DM)." (PMID 36232780, 2022).
diabetes (continued). "As the most common metabolic illness worldwide, diabetes alters the insulin, glucose, cortisol and lipoprotein profiles of the body significantly." (PMID 35964948, 2022). "Abnormal secretion of Amylin was found to coincide with disturbance in insulin secretion in pre-diabetes and late phases of T2DM." (PMID 35682821, 2022). "The additional findings related to diabetes management (insulin injection or insulin pump) and BMI classifications (e.g., overweight and obese) are presented in the appropriate section." (PMID 36508408, 2022). "In the case of diabetes, it states if there is a need for the patient to uptake insulin (Yes as Y) or if there is a need to uptake insulin along with other medicine (No as N)." (PMID 36433212, 2022). "T1DM is known as insulin-dependent diabetes mellitus because of the body’s inability to synthesize insulin, the hormone that regulates blood glucose in the body." (PMID 35301410, 2022). "The current COVID-19 pandemic has highlighted the fact that patients with comorbidities such as diabetes have an increased SARS-CoV-2 susceptibility and further complications, which include insulin resistance and lipid metabolic dysregulation." (PMID 36138787, 2022). "Patients unable to give informed consent.Patients with a known allergy to the disinfectants.Patients currently using antimicrobials, immunosuppressant drugs, or insulin for uncontrolled diabetes.Patients with an open wound." (PMID 36124902, 2022). "Type 2 diabetes mellitus (T2D) is the most common endocrine metabolic disorder, characterized by impaired insulin response and insulin resistance." (PMID 35054496, 2022). "The opposite situation was found in the group with DM who did not have DR as a complication, meaning that the majority were using OADs as diabetes treatment (10/13 subjects) and that only 3/10 subjects had started insulin-based medication." (PMID 35888628, 2022). "Further, gut microbial vitamin production was related to factors directly and indirectly related to diabetes, including blood glucose, insulin, HOMA-IR, lipids, circulating inflammation, and fecal SCFAs." (PMID 36474346, 2022). "A combination of physical activity and a proper diet is an important part of the management strategy for patients with diabetes, as it contributes to increasing cellular sensitivity to insulin." (PMID 36555387, 2022). "Antidiabetic effects of cafestol were reported in male KKAy mice (a strain with metabolic abnormalities used for diabetes and obesity research), where cafestol increased insulin secretion from isolated islets by 75–87%." (PMID 36632095, 2022). "People with diabetes show an impaired function of insulin (insulin resistance) and therefore need an increased amount of insulin than β cells (in the pancreas of a person) can produce." (PMID 35057501, 2022). "As current therapies focusing on increasing insulin sensitivity and/or insulin secretion fail to cure diabetes, one potentially underappreciated target for diabetes treatment is the alpha-cell." (PMID 35957816, 2022). "Diabetes is a serious lifelong disease, always characterized by abnormally high blood glucose levels due to insulin production disorder or decreased insulin sensitivity and function." (PMID 35725834, 2022). "There is a consensus that supports the use of insulin for people with diabetes who are hospitalised with SARS-CoV-2 infection." (PMID 35256883, 2022). "We further assessed the ability of that IDE-inhibiting antibody to improve insulin activity in vivo in an STZ-induced diabetes mouse model." (PMID 35350789, 2022). "Serum RBP4 levels are also found to be elevated in insulin-resistant mice and humans with obesity and diabetes." (PMID 35369314, 2022). "Our study pins the role of miRNA-21 in modulating brain insulin signaling and hence alleviating cognitive dysfunction accompanying diabetes mellitus." (PMID 35781592, 2022).
diabetes (continued). "In line with that result, an 11-year follow-up investigation of the Paris Prospective Study demonstrated that fasting plasma insulin level was an independent predictor of cardiovascular disease death after adjusting for overt diabetes." (PMID 35090539, 2022). "Diabetes is a metabolic disease that occurs due to insufficient release of insulin from the pancreas or the development of insulin resistance." (PMID 37551286, 2022). "Treatment of diabetes with insulin is a prime example for mathematical modelling that can now be applied to suggest personalized dosing schemes." (PMID 35748700, 2022). "As a consequence, this type of diabetes involves defects in both insulin secretion and insulin action." (PMID 35729232, 2022). "The current treatments for diabetes involve artificial insulin and blood glucose regulation by oral or intravenous medications." (PMID 36128718, 2022). "Eubacterium_hallii_group ferment dietary fibers to metabolize butyric acid and propionate through intestinal microbes, thereby regulating insulin sensitivity, reducing inflammation, and improving diabetes in humans and mice." (PMID 36081798, 2022). "In the study done in Saudi Arabia, only 13% of patients with diabetes increased their insulin dose during illness." (PMID 35846869, 2022). "Providing patients with life‐long exogenous insulin is extremely important for the treatment of diabetes." (PMID 36176618, 2022). "The patient was treated with an insulin pump combined with acarbose (50 mg, bid) for his secondary diabetes and a platelet-booster capsule for thrombocytopenia." (PMID 36401425, 2022). "While defects in insulin signaling are central to diabetes pathogenesis, the effect of insulin signaling on GNG appears to be largely indirect through substrate availability." (PMID 36402444, 2022). "Suppression of postprandial insulin secretion was observed with other ONS for diabetes and low-glycemic index diets." (PMID 35745116, 2022). "They adapted the STZ-induced diabetes mouse model to study the effect of thrombomodulin on glucose metabolism and insulin secretion." (PMID 35454311, 2022). "For pulmonary drug delivery, in 1925, Gänsslen first reported the blood-glucose-lowering effect of inhaled insulin in five subjects with diabetes." (PMID 36145722, 2022). "Some of the authors describe its inhibiting effect on glucose-stimulated insulin release from human and rodent models of diabetes mellitus, while others implicate it in basal or glucose-induced insulin release in humans." (PMID 35628187, 2022). "Pathway analysis of these genes revealed ‘insulin secretion’ as the most represented, as well as other glucose-metabolism-related pathways including ‘maturity-onset diabetes of the young’ and ‘type 2 diabetes mellitus’." (PMID 35802167, 2022). "Future studies using randomised control trial design would be useful for evaluating physical activity to prevent diabetes and delay progression of non-insulin dependent to insulin-dependent diabetes in PLWH and HIV-uninfected populations in SSA." (PMID 35992098, 2022). "Insulin therapies for patients with diabetes have challenges, including diminished hepatic preference of insulin action compared with endogenous insulin." (PMID 35177603, 2022). "Those patients with multiple major complications of diabetes and CAD are more likely to be treated with insulin and control the established risk factors such as hypertension and dyslipidemia, which are closely associated with MACE." (PMID 35782452, 2022). "Several independent clinical studies and meta-analysis confirmed that insulin use increased the risks of DME in patients with type 2 diabetes mellitus (T2DM) compared with oral hypoglycemic agents." (PMID 35937830, 2022). "The clinical manifestation of diabetes occurs only after the death of 80–90% of all insulin-producing cells." (PMID 35409018, 2022).
diabetes (continued). "Among others, mHealth apps for diabetes include the following management tasks: glucose monitoring, insulin delivery, nutrition, physical activity, facilitation of communication with healthcare providers or diabetes support groups, and education." (PMID 35673501, 2022). "The approximate average life spans with diabetes and insulin use of the participants were 12 and 5 years, respectively." (PMID 35854336, 2022). "PAHSA levels in SQ WAT and serum correlate positively with insulin sensitivity in humans and mice, and levels are reduced before overt diabetes occurs in people with insulin resistance." (PMID 35676490, 2022). "Studies have shown that EPA and DHA, such as deep-sea fish oil, can improve insulin resistance and decrease fasting serum insulin levels to some extent in patients with diabetes." (PMID 36698925, 2022). "All patients with diabetes who developed hypoglycemia happened to be treated with insulin, together with appropriate lifestyle advice (and other medications as appropriate for T2D)." (PMID 36011166, 2022). "Proper diabetes management requires consideration of various factors including tailored food intake, medication, insulin levels, and physical activity, in the hope to achieve precision control for each patient." (PMID 36743935, 2022). "The objective of this study was therefore to explore the lived experiences of diabetes patients regarding access to insulin and oral diabetes medicines in Zimbabwe." (PMID 36962297, 2022). "Type 1 diabetes mellitus (T1DM), arising from a complex interaction between immune, genetic and environmental factors, results from autoimmune-mediated destruction of insulin-producing pancreatic β-cells in genetically predisposed individuals." (PMID 36093078, 2022). "This glucose-activatable LbL microspheres system can be a promising alternative in diabetes therapy and serve as a powerful tool for constructing a precisely controlled INS release system." (PMID 36246353, 2022). "As a chronic metabolic disease, diabetes is characterized by hyperglycemia due to defective insulin secretion, impaired biological insulin action, or both and usually results from environmental factors and genetic interactions." (PMID 36553697, 2022). "At present, the main drugs for the treatment of diabetes complicated with myocardial injury are hypoglycemic agents and insulin secreting agents." (PMID 35401934, 2022). "Dining patterns have changed to Westernized eating habits since industrialization, which has also affected the development of diabetes, closely related to insulin secretion." (PMID 36292424, 2022). "A new source of insulin-producing cells would represent a significant step forward in cell therapy for the treatment of diabetes." (PMID 36090777, 2022). "Diabetes is a chronic disease characterized by hyperglycemia, in which the body is unable to produce enough insulin or the action of insulin is impaired." (PMID 36335331, 2022). "In this pre-clinical study, we demonstrated the effect of an alum-formulated, multi-dose insulin peptide vaccine on T1D development when administered during late-stage pre-diabetes." (PMID 36339431, 2022). "Some CPPs have been applied for the delivery of peptide antidiabetics, including insulin and exendin-4, for treating diabetes and Alzheimer’s disease." (PMID 36452220, 2022). "In type 2 diabetes mellitus, which is the most common type of diabetes, hyperglycemia is the result of an inadequate production of insulin and insulin resistance, which means that the body cannot fully respond to insulin." (PMID 35422003, 2022). "IDE is a zinc metalloprotease that is present in the cytosol of all cells, degrades many small proteins, including insulin and amyloid, and is also involved in the pathogenesis of diabetes and Alzheimer’s disease (AD)." (PMID 35992696, 2022).